TNF (tumor necrosis factor)
Diseases named in the same sentence as TNF in open-access papers (continued):
Sharing a sentence is not in itself a finding about the gene and the disease.
Insulin resistance (continued). "Overall, it may suggest that miRNA-126 would improve the insulin resistance through regulating NF-κB signaling and secretion of inflammatory biomarkers including TNF-α and IL-6." (PMID 34077450, 2021). "Hence, TNF-α is well known to be an important mediator of insulin resistance in adipose tissue through insulin-receptor signaling in rodents and humans." (PMID 33954196, 2021). "In addition, it has been proven that TNFα induces insulin resistance by interfering with insulin signaling directly and indirectly." (PMID 34068151, 2021). "However, as more studies demonstrated a correlation between systemic inflammation and insulin resistance, it is plausible to assume the impact of anti-TNF is based on the anti-inflammatory effect." (PMID 32776224, 2021). "Smaller adipocytes retain their insulin sensitivity, while hypertrophied adipocytes are likely to become insulin resistant and secrete proinflammatory cytokines, such as tumor necrosis factor-alpha (TNFα) and interleukin 6 (IL-6), which can also induce insulin resistance in other tissues." (PMID 33671850, 2021). "Indeed, compared to the body weight loss group, the group of obese women exhibited a high level of MEK6 expression, and in 3T3-L1, the MEK6 pathway promoted the induction of insulin resistance by tumor necrosis factor-α (TNF-α) and the process of adipogenesis." (PMID 34948353, 2021). "Neutralisation of TNF-α in these animals led to a decrease in insulin resistance." (PMID 34900829, 2021). "This drug induces inflammatory reactions in insulin resistance by inhibiting TNF-α and IL-6." (PMID 34037093, 2021). "On the contrary, IL-10 produced by M2 ATMs can relieve TNF-α-induced insulin resistance." (PMID 34108967, 2021). "TNF-α overexpression has been strictly correlated to adipose tissue dysfunction resulting in inflammation, augmented lipolysis, impairment of glucose uptake and insulin resistance (IR)." (PMID 34361563, 2021). "Conversely, negative correlations were observed between miRNA-126-3p and miRNA-146a levels and TNF-α (r = -0.7 and r = -0.82 respectively), IL-6 (r = -0.65 and r = -0.78 respectively) as well as insulin resistance (r = -0.67 and r = -0.78 respectively) (all p<0.05)." (PMID 34077450, 2021). "For instance, elevation in circulating TNFα levels (observed in tissues such as adipose and muscle (Saghizadeh, Ong, Garvey, Henry, & Kern, 1996)) causes a downstream activation of stress kinases, triggering TNF‐mediated insulin resistance and glucose dyshomeostasis." (PMID 31407867, 2020). "Moreover, the expression of TLR2, TNF-α and IL-1β in old mice is also increased, thereby inhibiting Akt and mTOR activity and promoting insulin resistance." (PMID 32082422, 2020). "In addition, MS-275 treatment of HF/HFr-fed mice ameliorated insulin resistance, stress-related signaling, and TNF-α expression in skeletal muscle." (PMID 33362555, 2020). "In addition, it is well described in the literature that TNF-α reduction is able to attenuate insulin resistance, which in turn is the main condition for the onset of diabetes mellitus and consequently various ocular diseases." (PMID 32847099, 2020). "Interestingly, TNF-α and estradiol balance plays an important role in development of insulin resistance." (PMID 32635208, 2020). "TNF-α also induces lipolysis, producing circulating lipids, thereby inducing insulin resistance." (PMID 33266423, 2020). "It has been demonstrated that persistent elevation of the level of TNF-α induces insulin resistance and pancreatic β-cell dysfunction and thus exacerbates hyperglycemia, which could accelerate the onset of diabetes." (PMID 32509152, 2020). "Thus, IL-6- or TNF-α-dependent insulin resistance is mediated, at least in part, by the induction of SOCS proteins in insulin target cells." (PMID 33255404, 2020).
Insulin resistance (continued). "The altered adipokines and pro-inflammatory cytokines such as IL-6, TNF-α, and MCP-1 which secreted from adipose tissue may directly or indirectly caused insulin resistance through impairing insulin signaling or activating pro-inflammatory pathways." (PMID 32265835, 2020). "T2DM is characterized by insulin resistance and chronic low-grade inflammation with abnormal production of inflammatory mediators such as tumor necrosis factor-α (TNF-α) and interleukins; this is often unknown until high blood glucose levels are observed." (PMID 32290852, 2020). "In a recent study, inhibition of C–C chemokine receptor 2, the MCP-1 receptor, ameliorated insulin resistance and hepatic steatosis by regulating hepatic lipid homeostasis in type 2 diabetic model mice, and anti-TNF-α treatment improved hepatic steatosis and insulin resistance." (PMID 32182914, 2020). "We used TNF-α to induce insulin resistance in human myotubes." (PMID 32393961, 2020). "This increase happens in response to their hyperglycemia and it might play an important role in the development of hyperandrogenism and insulin resistance through the activation of NF-κB and increased transcription of the TNF-α gene." (PMID 32187268, 2020). "For instance, IL-6 increases glucose uptake, lipolysis, and oxidation of FFA and mediates anti-inflammatory effects by inducing expression of cytokines such as IL-10 and inhibiting expression of TNFα, which induces insulin resistance and mitochondrial dysfunction in myocytes in vitro." (PMID 32397353, 2020). "The M1 macrophage may promote the development of insulin resistance through secretion of proinflammatory cytokine such as TNF-α, IL-6, and IL-1b in response to stimulation by INF-γ." (PMID 32971975, 2020). "Another cytokine released by adipose tissue is TNF-α that may affect the development of insulin resistance." (PMID 32375231, 2020). "MCP-1, a chemoattractant protein that recruits immune cells to sites of inflammation, and TNF-α, a pro-inflammatory cytokine that inhibits insulin secretion and induces apoptosis of β-cells, also play pivotal roles in the development of insulin resistance and hepatic steatosis." (PMID 32182914, 2020). "Moreover, TNF-α by inducing serine phosphorylation of insulin receptor substrate-1 can act as an inhibitor of peripheral insulin action which leads to insulin resistance." (PMID 32089876, 2020). "Also, studies have found the role of TNF-α in insulin resistance in obese patients, suggesting its involvement in DM2." (PMID 33489600, 2020). "The activated ATMs then secrete various proinflammatory cytokines, such as TNF-α and interleukin-1β (IL-1β), which could lead to systemic insulin resistance due to endocrine actions." (PMID 33208918, 2020). "As TNF-a and IL-6 are known to induce insulin resistance, stimulate androgen production and disrupt the hypothalamic-pituitary-ovarian axis, the increased number of lymphocytes could be an factor triggering chronic inflammation and altered hormone secretion." (PMID 32103756, 2020). "Among the various inflammatory mediators, leptin, IL-6 and TNF-α are the major pro-inflammatory mediators that paly their decisive role to induce the inflammatory responses during the pathogenesis of DM and development of insulin resistance." (PMID 31929574, 2020). "In addition to its role in modifying adipose tissue function and expandability, enhanced production of TNF can also induce vascular insulin resistance, which in turn promotes premature endothelial cell death and premature aging of coronary arteries." (PMID 33330676, 2020). "Nicotine may mediate these pathways, as it increases insulin resistance, possibly through increased ROS production and TNF-α expression." (PMID 32379818, 2020). "In addition, paeonol and its major metabolites improved TNF-α mediated insulin resistance in 3T3-L1 adipocytes." (PMID 32180731, 2020).
Insulin resistance (continued). "These signaling pathways, which may be activated by TNFα, free fatty acids, ROS, and hypoxia, cause serine kinase phosphorylation of IRS-1 or IRS-2, which blocks insulin signaling and subsequently, causes insulin resistance." (PMID 32971975, 2020). "Correlations of IL-6, leptin and TNF-α with diabetes have been explored extensively, and most of these studies obtained results similar to ours that TNF-α, IL-6 and leptin were positively associated with insulin resistance or secretion." (PMID 33292292, 2020). "Another report demonstrated that plasma SAM levels were associated with cardiometabolic risk factors such as higher fasting insulin levels, homeostasis model assessment of insulin resistance and TNF-α in a cross-sectional study in humans with metabolic syndrome." (PMID 32145700, 2020). "Fat accumulation in the visceral adipose tissue and liver has been shown to increase the secretion of proinflammatory cytokines, such as tumor necrosis factor (TNF)-α, interleukin (IL)-1, IL-6, and leptin, leading to metabolic tissue inflammation and insulin resistance in obese individuals." (PMID 32917958, 2020). "Moreover, mice deficient in TNF-α have lower levels of circulating FFA, which are a potential cause of the development of insulin resistance." (PMID 33322719, 2020). "Therefore, puerarin can decrease the expression of TNF-α and ameliorate insulin resistance in GDM rats, suggesting the potential efficacy of puerarin in GDM treatment." (PMID 32946041, 2020). "When adipose tissue expands to a great extent, TNFα contributes to insulin resistance." (PMID 32297262, 2020). "DAVID results indicated that TwHF may play a role in treating DKD through AGE-RAGE signaling pathway, IL-17 signaling pathway, TNF signaling pathway, insulin resistance, and calcium signaling pathway (P < 0.05)." (PMID 33274236, 2020). "At baseline and post-intervention, anthropometrics, body composition, systemic inflammation (high-sensitivity C-reactive protein, tumor necrosis factor-α, and interleukin 6), fasting glucose, insulin and homeostasis model assessment-insulin resistance (HOMA-IR) were determined." (PMID 33126555, 2020). "Most studies found that subjects with insulin resistance or T2DM had increased levels of TNF-α." (PMID 33013895, 2020). "However, clinical trials targeting TNF-α have generally shown little or no beneficial effect on systemic insulin sensitivity, indicating that TNF-α lowering is insufficient to combat insulin resistance in humans." (PMID 33072120, 2020). "Not only IL6 and TNF-α increase but insulin resistance develops as well." (PMID 33643281, 2020). "In addition, TNF-α induces lipolysis, generating circulation lipids and inducing insulin resistance." (PMID 33266423, 2020). "Inflammatory cytokines such as TNF-α play a major role in insulin resistance." (PMID 32695286, 2020). "Exercise suppresses the production of TNFα, which is known to cause insulin resistance through skeletal muscle IL-6 secretion without weight loss while inducing secretion of anti-inflammatory cytokines to improve systemic inflammation." (PMID 32954935, 2020). "Resistin also acts by stimulating proinflammatory cytokines such as TNF-α and IL-12, and may be the link between inflammation and insulin resistance in an inflammatory environment." (PMID 32130282, 2020). "The role of TNF-α and IL-6 in insulin resistance has remained controversial." (PMID 33066473, 2020). "In addition, growing evidence reveals that dyslipidaemia is associated with increased levels of certain inflammatory mediators, including TNF-α and IL-6, which play a critical role in producing insulin resistance." (PMID 33322742, 2020). "Finally, inflammation has been found to be related to obesity-induced insulin resistance in people with type 2 diabetes, as inflammatory cytokines such as TNF can directly induce insulin resistance." (PMID 32467827, 2020).
Insulin resistance (continued). "Similarly, mice in which Ccl2 had been deleted showed resistance to high fat diet-induced insulin resistance and hepatic steatosis, an effect that was accompanied by reduced expression of TNFα in adipose tissue." (PMID 32158768, 2020). "A variety of experimental and clinical studies suggest that TNFα may act as an essential auto/paracrine regulator in fat cells which limits the AT spreading but increases insulin resistance, leading to some metabolic disorders." (PMID 33278072, 2020). "Besides lipotoxicity, local inflammation also occurs, with the secretion of TNF-α by adipocytes and macrophages attracted to adipose tissue and consequently insulin resistance." (PMID 32824505, 2020). "TNF-α-induced phosphorylation of IRS-1 at Ser 307 leads to insulin resistance in liver cells, and a JNK inhibitor largely abolishes the phosphorylation of IRS-1 at Ser 307 and restores insulin resistance, indicating that JNK activity is involved in the mechanism of TNF-α-induced insulin resistance." (PMID 32842547, 2020). "A previous report demonstrated that plasma SAM concentrations were related to higher fasting insulin levels, the homeostasis model assessment of insulin resistance, and the tumor necrosis factor α in a cross-sectional study that involved subjects with metabolic syndrome." (PMID 32850834, 2020). "Therefore, TNF plays a crucial role in the development of insulin resistance in several tissue types with high glucometabolic relevance." (PMID 33178196, 2020). "Similarly, female Sprague-Dawley rats and female BALB/c mice, after 8 weeks of treatment (10 mg/kg/day), exhibited a significant increase in TNF-α, IL-6, IL-1β, and IL-8 levels, in addition to insulin resistance." (PMID 32373066, 2020). "TNF signaling pathway: tumor necrosis factor-alpha (TNF-α), one of the most crucial pro-inflammatory mediator, induced insulin resistance in adipocytes by impairing the insulin signaling through serine phosphorylation so that leading to the development of T2DM." (PMID 33292335, 2020). "Subsequently, Hotamisligil and Karasik first showed that that the overproduction of the proinflammatory cytokine tumor necrosis factor-alpha (TNF-α) by adipocyte tissue could induce insulin-resistance." (PMID 32153503, 2020). "Also, out of 28 patients with chronic olanzapine consumption (unspecified dose) 14 were insulin-resistant and had a higher concentration of TNF-α, IL-6, IL-1β, and IL-8 with a positive correlation between these values and insulin resistance." (PMID 32373066, 2020). "The decline of IL-10 and elevation of TNF-α and IL-6 are reported to be important regulators underlying insulin resistance and a slow nonhealing chronic wound process." (PMID 32879654, 2020). "Furthermore, the administration of IL-10 improved the insulin resistance after lipid infusion, increased the glucose uptake in isolated adipocytes and diminished the insulin resistance induced by TNF-α." (PMID 32824505, 2020). "M1 macrophages release factors, such as TNFα and IL1β, that promote inflammation and are thought to potentially contribute to insulin resistance; in contrast, M2 macrophages are activated by Th2 cytokines, resolve inflammation, and induce extracellular matrix (ECM) remodeling." (PMID 32408016, 2020). "In line with previous reports, we also identified a positive association of systemic IL-6 levels with insulin resistance, whereas other cytokines (IL-1ß, TNF, IL-10) did not correlate significantly." (PMID 33349270, 2020). "Interestingly, a recent meta-analysis also showed that probiotics reduced liver transaminase, total cholesterol, TNF-α, and insulin resistance in NAFLD patients." (PMID 32483129, 2020). "The increase in macrophages and other immune cells in psoriatic lesions and the synovio-entheseal complex would promote complex metabolic changes in the liver and adipose tissue, especially insulin resistance, as well as increased release of TNF-α and lower production of adiponectin." (PMID 32028959, 2020).
Insulin resistance (continued). "Secretion of adipokines (e.g. leptin) and cytokines (e.g. TNF-α, IL-6 and IL-1β), oxidative stress and, possibly, the gut microbiome contribute to pregnancy-induced insulin resistance, although understanding of pregnancy-induced insulin resistance is incomplete." (PMID 32556615, 2020). "In addition, the neutralization of TNF-α with a soluble TNF receptor attenuates insulin resistance in obese mice." (PMID 32774333, 2020). "Finally, anti-TNF-α compounds like etanercept, infliximab, and adalimumab were also shown to reduce insulin resistance in T2D." (PMID 33143088, 2020). "While the regulation of insulin responses and development of the pathophysiology of insulin resistance due to overexpression of TNFα and other pro-inflammatory cytokines is well documented, the functional links and interactions that mediate insulin resistance are complex and largely unexplored." (PMID 33257747, 2020). "The group of pro-inflammatory cytokines including TNF-α, IL-6, and IL-1β inhibit lipoprotein lipase in adipocytes, thereby increasing the lipolysis and secretion of circulating free fatty acids, leading to insulin resistance." (PMID 33182462, 2020). "TNF-α is involved in glucose and insulin metabolism, lipolysis, and insulin resistance." (PMID 32188105, 2020). "Furthermore, phloretin reduce the levels of TNF-α in the liver and epididymal adipose tissue, improving inflammation and insulin resistance." (PMID 33014333, 2020). "TNFα may increase systemic insulin resistance by promoting the release of fatty acids from adipose tissue into the bloodstream to act on tissues, such as muscle and liver tissues." (PMID 30658634, 2019). "IL-10 is an anti-inflammatory cytokine that alleviates the TNFα-induced insulin resistance." (PMID 31357412, 2019). "Animal and human studies also support the link between TNF-α and insulin resistance." (PMID 29955954, 2019). "However, the attribution of TNF-α expression in pathogenesis of palmitate-induced insulin resistance and inflammation in liver cells is poorly described." (PMID 30863203, 2019). "We supposed that SHED administration via the tail vein downregulated the serum levels of IL-1 and TNF-α and upregulated those of IL-10 in DN rats, not only improving insulin resistance but also affecting the renal immune response through inflammatory cytokines." (PMID 31871464, 2019). "Plasma Cer level has been reported to be elevated in type-2 diabetic subjects and may contribute to insulin resistance through activation of inflammatory mediators, such as TNF-α." (PMID 31031634, 2019). "Also, TNFα is a mediator of insulin resistance, thus it is likely dietary-induced inflammation, is the base of insulin resistance in PCOS." (PMID 32133054, 2019). "In mice, administration of exogenous TNF-α could lead to insulin resistance, conversely neutralization of TNF-α improved insulin sensitivity." (PMID 31736870, 2019). "TNF and IL-6 could impair intracellular insulin signalling, potentially leading to insulin resistance." (PMID 31387569, 2019). "Inflammation and insulin resistance are closely related, and inflammatory cytokines such as TNF-α, IL-6, IL-1, and IL-8 may inhibit insulin signaling via multiple mechanisms." (PMID 31118902, 2019). "In addition, adipokines secreted by visceral adipose tissue, such as leptin, adiponectin, and TNF-α, play a key role in the tissue sensitivity to insulin, favoring the onset of insulin resistance and tissue inflammation." (PMID 30944697, 2019). "The timing and the degree of vascular insulin resistance induction may be dependent on exposure time and/or concentration of TNFα." (PMID 31013778, 2019). "The inhibition of TNF-α and IL-6 production may be one of the options for preventing the development of insulin resistance and the pathogenesis of T2DM." (PMID 30871060, 2019).